EGFR (epidermal growth factor receptor)
Diseases named in the same sentence as EGFR in open-access papers (continued):
Sharing a sentence is not in itself a finding about the gene and the disease.
adenocarcinoma (continued). "These samples encompassed diverse histologies, including adenocarcinoma, combined SCLC/NSCLC collected prior to EGFR-TKI treatment, and transformed SCLC (t-SCLC) after EGFR-TKI therapy." (PMID 41516316, 2025). "Rebiopsy (bronchoscopy) 16/08/2023 (HP + IHC + Genetic tests: poorly differentiated adenocarcinoma; ALK, EGFR, PD-L1 positive) low expression (TPS = 5%)." (PMID 40429388, 2025). "In patients with non-small cell lung cancer (NSCLC), activating alterations in the epidermal growth factor receptor (EGFR) are present in about 10% of patients, mostly those with adenocarcinoma." (PMID 39858040, 2025). "About 97.3% had adenocarcinomas, with 93.6% at stage IV, 40.9% with ≥ three metastatic sites (brain metastases in 24.5%), 33.6% ECOG 2–4, and 58.2% with an EGFR exon-19 deletion." (PMID 40862783, 2025). "Immunohistochemical results showed EGFR positivity in 8.7% of GERD patients (11/127), 25% of BE patients (6/24), and 46.5% of adenocarcinoma patients (20/43), with statistically significant differences among the groups (p = 0.0001)." (PMID 40149421, 2025). "The pathological study reported poorly differentiated adenocarcinoma, with immunohistochemistry showing CK5/6 (-), P40 (few +), EGFR (sp111) (1+), EGFR (sp125) (+), CK7 (+), TTF-1 (+), Ki-67 (60%+), VENTANA ALK (D5F3) (-), BRAF (-), and PD-L1 (Daco 22C3) < 1%." (PMID 39654211, 2024). "The same trend was observed for the adenocarcinoma cases (0.333 in the ALK group and 0.101 in the EGFR group; p < 0.001)." (PMID 38400801, 2024). "The same analysis was done for the adenocarcinoma cases, in which 96 patients received ALK–TKIs and 135 patients received EGFR–TKIs." (PMID 38400801, 2024). "For adenocarcinoma cases only, CEA positivity was also significantly lower in the ALK group (49%) compared with 71% in the EGFR group (p < 0.001)." (PMID 38400801, 2024). "Histologic transformation from adenocarcinoma to SCLC arises in 4–15% of patients with EGFR-mutant NSCLC that develops an acquired resistance to first- and third-generation EGFR-TKIs." (PMID 39456595, 2024). "However, we can anticipate that the identified group of interest will likely include young female patients with adenocarcinoma histology, never or light smokers, patients with EGFR mutations, patients with a history of multiple primary tumors, and patients with a high burden of family history." (PMID 39085889, 2024). "Although these cells are classified as Adenocarcinoma, their outgrowth patterns vary depending on their oncogene expressions (KRAS or EGFR)." (PMID 39180048, 2024). "In analyses of only those patients with adenocarcinoma, the median CEA level was 5.2 ng/mL in the ALK group and 17.3 ng/mL in the EGFR group, with a statistically significant difference (p = 0.007)." (PMID 38400801, 2024). "In the first-generation EGFR-TKI resistance cohort, a 74-year-old female was diagnosed with TTF-1-positive adenocarcinoma." (PMID 39456595, 2024). "These cells, both categorized as adenocarcinomas, had distinct genetic profiles: one harboring the KRAS oncogene (HCC 4087) and the other the EGFR oncogene (HCC 4190)." (PMID 39180048, 2024). "Soon after, she was diagnosed with a poorly differentiated NSCLC adenocarcinoma stage IIIB, with an EGFR exon 19 deletion." (PMID 36923435, 2023). "In our study, we initially assessed the genomic alterations and clinical outcomes among patients diagnosed with adenocarcinoma that underwent transformation to SCLC following treatment with first/second-generation and third-generation EGFR-TKIs." (PMID 38188289, 2023). "Mean (standard deviation [SD]) age for 1073 patients with EGFR-wild-type/ALK-wild-type mNSCLC was 66.2 (8.9) years, 65.2% were male and 63.7% had adenocarcinoma." (PMID 37386452, 2023). "Several studies have revealed a strong expression of the epidermal growth factor receptor (EGFR), a transmembrane glycoprotein and member of the tyrosine kinase growth factor receptor superfamily, in 32 to 47% of G/GEJ adenocarcinomas." (PMID 37046849, 2023).
adenocarcinoma (continued). "Interestingly, our findings suggested that EGFR-mutated adenocarcinoma with micropapillary components may not respond to treatment with EGFR-TKIs." (PMID 34652430, 2022). "Genistein alters growth factor signaling by downregulating tyrosine kinase-regulated proteins, epidermal growth factor receptor (EGFR), and IGF-1R in transgenic adenocarcinoma in mouse prostate models." (PMID 36430361, 2022). "Genistein alters growth factor signaling through downregulation of tyrosine kinase-regulated proteins, EGFR, and IGF-1R in transgenic adenocarcinoma of the mouse prostate model." (PMID 36430361, 2022). "Female (p < 0.001), non-smoker (p < 0.001), adenocarcinoma (p < 0.001), non-brain metastasis (p < 0.001), tissue specimens (p < 0.001), patient from the coal-producing area (p < 0.05) and non-Fuyuan country origin patients (p = 0.007) appeared to be associated with a higher EGFR gene mutation rate." (PMID 35606799, 2022). "Herein, we suggested that EGFR-mutant and HER2-mutant patients had a similarly low PD-L1 expression rate to that of wild-type adenocarcinoma patients." (PMID 35980949, 2022). "Adenocarcinomas harbor targetable genomic alterations in ALK, BRAF, EGFR, and ROS1 genes, and novel treatment options such as KRAS Gly12Cys, MET, NTRK, and RET inhibitors, and possibly ERBB2 guided therapies are broadening the clinical repertoire." (PMID 35964518, 2022). "Although ctDNA is approved for the detection of EGFR mutant in NSCLC patients, adenocarcinomas are more likely to be detected by the established miRNA markers over squamous cell carcinoma." (PMID 35209919, 2022). "USP22 activates multiple EGFR downstream signaling pathways, including the STAT3, AKT/mTOR, and MEK/ERK pathways, in lung ADC (adenocarcinoma) cell lines H1975 and PC9, and it stabilizes EGFR protein expression." (PMID 34502538, 2021). "In human pancreatic (PANC-1) and colorectal (HT-29) adenocarcinoma cell lines, NDRG1 markedly reduced total EGFR levels, inhibited EGFR dimerization and activation, and lowered EGFR phosphorylation even in the presence of EGF." (PMID 35008802, 2021). "The aera of personalized treatment, the introduction of targeted therapy was most frequent at adenocarcinoma, especially at young patients (ALK inhibitors), while in older women, the possibility of EGFR inhibition resulted in visible improvement." (PMID 34257563, 2021). "Multicollinearity is also a noteworthy issue considering that DM patients with high HbA1c levels tended to be males, elders, smokers, obese, non-adenocarcinoma, with CVD and wildtype EGFR." (PMID 34868942, 2021). "Three isogenic erlotinib-resistant cell lines (ER10, ER20, ER30) were generated from the adenocarcinoma NSCLC cell line, HCC827 (EGFR exon19del) as described in “Methods”." (PMID 34267282, 2021). "Our study provided a real-world treatment response of combination EGFR TKI and anti-angiogenesis in adenocarcinoma of the lung with MPE." (PMID 34680445, 2021). "In contrast, higher stage, nonacinar and nonlepidic adenocarcinoma subtype, sublobar resection, positive resection margins, and lymphovascular invasion were associated with recurrence on both univariate and multivariate analyses among patients with EGFR-positive NSCLC." (PMID 34739062, 2021). "EGFR was visualized as a green color by FITC, and 4′,6-diamidino-2-phenylindole (DAPI) was used to stain the nuclei of adenocarcinoma cells in blue." (PMID 34502049, 2021). "With discrepancy in TKI outcomes, EGFR-mutant SCC and adenocarcinoma, however, presented similar genomic patterns." (PMID 34195081, 2021).
adenocarcinoma (continued). "This approach was then used for profiling the membrane proteinof sEVs isolated from NSCLC H1975 cell culture media after treatmentwith the EGFR-TKIs erlotinib and osimertinib, as well as sEVs obtainedfrom PE-fluid of NSCLC adenocarcinoma patients." (PMID 34473477, 2021). "Interestingly, the proportion of adenocarcinoma with the EGFR mutation was similar in the IPF and no-IPF groups in our study, which is in contrast to the results of previous studies that showed that patients with IPF had a lower EGFR mutation rate than no-IPF patients." (PMID 33859288, 2021). "Conversely, lower HER2 and higher EGFR and ERCC1 expression are detected in those adenocarcinomas with a solid pattern, which are less differentiated tumors." (PMID 33922215, 2021). "With the progression of the disease, mutations of EGFR L858R, PIK3CA H1047R, and ERBB2 S310F were detected in punctured lumbar tissues, and EGFR L858R and PIK3CA H1047R in ctDNA, consistent with the pathological characteristics of adenocarcinoma." (PMID 32508051, 2020). "The efficacy of EGFR tyrosine kinase inhibitors (TKI) in PSC has also varied between studies, and was inferior when compared to adenocarcinoma." (PMID 32149365, 2020). "Moreover, when stratifying patients for their characteristics, they found that there was a difference in survival and, consequently, a higher response rate to erlotinib, when patients were non-smokers, when they had EGFR mutation type exon 19 and adenocarcinomas." (PMID 32722386, 2020). "It is worth mentioning that their study was achieved in EGFR, K RAS, PI3KCA, HER2, and EML4-ALK wild-type adenocarcinoma only." (PMID 31781475, 2019). "Concurrent development of adenocarcinoma and SCLC was noted in EGFR-mutant tumors before treatment with an EGFR inhibitor." (PMID 35582592, 2019). "The odds of EGFR mutation were significantly higher (P < 0.0001) in females versus males (odds ratio 1.85; 95% confidence interval 1.48, 2.32), never smokers versus ever smokers (3.64; 2.91, 4.56), and adenocarcinoma versus other histological sub-types (2.94; 2.17, 4.08)." (PMID 29402243, 2018). "The efficacy of first line pemetrexed-based chemotherapy was investigated in patients with HER2-mutant and those with EGFR-mutant, ALK/ROS1-rearranged and KRAS-mutant advanced adenocarcinomas." (PMID 29587667, 2018). "A phase II study recently investigated a novel EGFR/HER2 inhibitor, pyrotinib, in heavily pre-treated patients with HER2-mutant adenocarcinomas and found a promising results with RR of 54.5%(6/11) and median PFS of 6.2 months." (PMID 29587667, 2018). "Because EGFR mutations are detected mostly in patients with an adenocarcinoma or non-squamous histology, the optimum regimen might be pemetrexed and platinum combination treatment, followed by maintenance pemetrexed for patients who did not suffer from disease progression." (PMID 29455650, 2018). "The responses show that all countries follow guidelines regarding EGFR and ALK testing, with most countries testing only advanced stages of adenocarcinomas, NSCLC-NOS, and NSCLC when an adenocarcinoma component cannot be excluded." (PMID 29523116, 2018). "For RFS, high CD73 expression (HR, 2.27; 95% CI, 1.47–3.51) was an independent unfavorable prognostic marker, after adjusting for age, sex, smoking status, stage, adjuvant chemotherapy, mutant EGFR expression, TTF-1 expression, and adenocarcinoma subtypes." (PMID 28060732, 2017). "Thus, EGFR tyrosine kinase inhibitor therapies could be effective for the type of adenocarcinoma." (PMID 28061855, 2017). "Eleven adenocarcinoma cases (25%) were double positive for EGFR and HER2 (EGFR+/HER2+/c-Met+ and EGFR+/HER2+/c-Met-)." (PMID 28859123, 2017). "In conclusion, our data indicate that CD73 and A2AR are more commonly expressed in adenocarcinoma, particularly TTF-1-positive and mutant EGFR-positive adenocarcinoma." (PMID 28060732, 2017).
adenocarcinoma (continued). "Among adenocarcinomas, significantly higher CD73 and A2AR expression was observed in TTF-1-positive and mutant EGFR-positive tumors than in their counterparts." (PMID 28060732, 2017). "The adenocarcinoma cell line OE33 on the other hand over-expresses HER2 and a small amount of EGFR (b 27)." (PMID 28128281, 2017). "Further analyses revealed that gefitinib use remained a strong predictor for longer PFS and OS in EGFR‐TKI responders, adherent patients, adenocarcinoma patients, and adenocarcinoma patients receiving EGFR‐TKIs as second‐line therapy." (PMID 28639751, 2017). "Twenty (46%) of the 43 adenocarcinoma cases were positive for multiple RTKs, including 7 cases (16%) with EGFR+/HER2+/c-Met+, 4 cases (9%) with EGFR+/HER2+/c-Met-, 3 cases (7%) with EGFR+/HER2-/c-Met+, and 6 cases (14%) with EGFR-/HER2+/c-Met+." (PMID 28859123, 2017). "The effects of various TKIs were consistent in the 4939 EGFR‐TKI responders, adherent subgroup, adenocarcinoma subgroup, and adenocarcinoma with second‐line TKIs subgroup." (PMID 28639751, 2017). "Retreatment with an EGFR TKI is not inferior to cytotoxic chemotherapy when used as salvage therapy for patients with adenocarcinoma with an EGFR mutation, especially if a third-generation EGFR TKI is not available, or if the reason for resistance is unknown or is not related to the T790M mutation." (PMID 28486985, 2017). "In the absence of a molecular predictor, never smoking Asians and patients of the adenocarcinoma subtype could represent a clinically select population with a high likelihood of harboring activating EGFR mutations and therefore more likely respond to EGFR-TKI." (PMID 28814805, 2017). "The EGFR mutation rate was significantly lower in the younger age group than in the older age group (53.3% versus 66.7%, P = 0.035) in never-smoking male patients with adenocarcinoma; and also in never-smoking female patients with adenocarcinoma (58.6% versus 69.9%, P = 0.001)." (PMID 27191886, 2016). "In general, NSCLC have more often activating mutations in important growth factor receptor signaling genes like EGFR and KRAS, although the percentage is lower in squamous cell NSCLC compared with adenocarcinoma NSCLC." (PMID 28031935, 2016). "Cox proportional hazards analysis of the impact of EGFR, HER2 and HER3 expression on recurrence-free and overall survival in patients with I-type adenocarcinoma." (PMID 27070783, 2016). "In the training cohort, most of these patients had adenocarcinoma histology (47/49; 95.9%), with progression-free survival (PFS) after EGFR-TKI > 6 months (46/49; 93.9%)." (PMID 27213587, 2016). "And the other possibility is preexistence of mixed SCLC and adenocarcinoma, with SCLC becoming dominant after EGFR-TKI therapy." (PMID 27488410, 2016). "The following day, we started EGFR-TKI therapy (erlotinib 150 mg orally every 24 h), after obtaining a definitive pathological diagnosis of adenocarcinoma by an immunohistochemical method." (PMID 25651992, 2015). "Our case highlights these recommendations in the idea that our patient had a light smoking history and if the biopsy had “missed” the adenocarcinoma portion and returned a pure squamous cytology or histology, one might have concluded that the patient was unlikely to have an EGFR mutation." (PMID 26366316, 2015). "One possible explanation is that the SCLC component exists prior to the EGFR-TKI therapy (combined SCLC), and SCLC emerges from regression of the adenocarcinoma in response to EGFR-TKIs." (PMID 26400668, 2015). "However, the impact of first-line platinum-based chemotherapy (CT) in female patients with EGFR mutated adenocarcinoma is a matter of debate and no definitive data emerge from subgroup analyses of randomized trials comparing CT with TKIs in the first-line setting." (PMID 25300933, 2014).
adenocarcinoma (continued). "In adenocarcinomas of the esophago-gastric junction (AEG) and the distal esophagus, EGFR expression has been found in approximately 30–60%, while EGFR gene amplification has been found in 8–31%." (PMID 25216514, 2014). "In EGFR and KRAS-wild type adenocarcinomas (EGFRwt/KRASwt), different potential drivers of pathogenesis exist, including ALK, RET, and ROS1 gene fusions, with ALK rearrangements being therapeutically relevant." (PMID 24205279, 2013). "Adenocarcinomas exhibit distinct genomic changes that can be classified into clinically relevant molecular subsets according to KRAS, EGFR, and EML4-ALK status." (PMID 23341890, 2013). "In 2004, mutations in the epidermal growth factor receptor (epidermal growth factor receptor, EGFR) gene were discovered in non-small cell lung cancers (NSCLC), especially in adenocarcinomas." (PMID 22989458, 2012). "A report presents a case of a never-smoking woman who presented with metastatic lung adenocarcinoma, cytokeratin, EGFR and TTF-1 positive by immunohistochemistry, consistent with adenocarcinoma of lung origin." (PMID 24213497, 2012). "KRAS and EGFR play pivotal roles in the development and growth of NSCLC, especially in patients with adenocarcinoma histology." (PMID 22992338, 2012). "In order to minimize the bias on the study results, we have taken a series of effective measures such as a panel of EGFR high and EGFR low ESCC cell lines and adenocarcinoma cell lines used in further study." (PMID 23232108, 2012). "Concurrent deletion in EGFR exon 19 and fusion of EML4-ALK was identified for the first time in a Chinese female patient with an adenocarcinoma." (PMID 20624322, 2010). "A proposed explanation has highlighted the coexpression of EGFR and high levels of HER2 in adenocarcinoma." (PMID 15187994, 2004). "Significant differences in gender (33.3% vs 62.3%, p=0.012), smoking history (22.2% vs 43.1%, p=0.063), and adenocarcinomas (100% vs 83.6%, p=0.028) were observed between primary BRAF/EGFR co-mutated and non-co-mutated groups." (PMID 40242250, 2025). "One of the most well-known examples is Epidermal Growth Factor Receptor (EGFR) mutations, present in 10–25% of NSCLC cases, more predominantly in adenocarcinomas, particularly among non-smokers, and more frequent in the Asian population." (PMID 40243903, 2025). "As for EGFR mutations and ALK fusions, ROS1 is more common for non-smokers and patients with an adenocarcinoma histology." (PMID 40136350, 2025). "Furthermore, EGFR expression was higher in BE tissues near areas of HGD and adenocarcinoma, suggesting its role in neoplastic transformation." (PMID 40149421, 2025). "EGFR mutations in NSCLC primarily occur in females, non-smokers, patients with adenocarcinoma, and Japanese patients." (PMID 40606988, 2025). "EGFR exon 20 insertions are also more common in women, never smokers, Asians, and patients with an adenocarcinoma." (PMID 40136350, 2025). "Clinically, EGFR-mutant patients are frequently characterized by non-smoking status, adenocarcinoma histology, female sex, and East Asian ethnicity." (PMID 40708937, 2025). "There are well-known facts on the association of NSCLC genotypes with such factors, e.g., EGFR mutations and ALK fusions prevail in female patients with adenocarcinoma of younger age and no history of smoking, while KRAS mutations are more common in smokers." (PMID 40809430, 2025). "As for EGFR mutations, ALK fusions are more common for never smokers and patients with adenocarcinoma histology." (PMID 40136350, 2025). "Ki values are lower in EGFR-expressing adenocarcinoma patients than in patients not expressing EGFR." (PMID 40297815, 2025).